ARHGAP35 (Rho GTPase activating protein 35)
Diseases named in the same sentence as ARHGAP35 in open-access papers (continued):
Sharing a sentence is not in itself a finding about the gene and the disease.
cancer (28 papers, 2014 to 2025). A tumor composed of atypical neoplastic, often pleomorphic cells that invade other tissues. "Despite the emergence of ARHGAP35 mutations as a new major cancer gene, few studies have investigated its implication for the prognosis and treatment of USC." (PMID 35949786, 2022). "The GTPase-activating protein (GAP) p190RhoGAP (p190A) is encoded by ARHGAP35 which is found mutated in cancers." (PMID 36516886, 2022). "Several large-scale studies mapping somatic variants across thousands of tumors identified ARHGAP35—the gene encoding p190A–as a new major cancer gene." (PMID 36516886, 2022). "ARHGAP35 (also known as p190RHOGAP) encoding glucocorticoid receptor DNA-binding factor-1 is a cancer associated gene with a mutation spectrum suggestive of a tumor suppressor function." (PMID 30886832, 2019). "Several large-scale studies mapping somatic variants across thousands of tumors recently identified ARHGAP35, the gene-encoding p190A, as a new major cancer gene." (PMID 31013840, 2019). "In 2013, ARHGAP35 appears among 127 significantly mutated genes from the analysis of 3281 tumors across 12 cancer types, with the highest percentage in uterine corpus endometrial carcinoma." (PMID 31013840, 2019). "Finally, we establish here that naturally occurring recurrent cancer mutations in ARHGAP35 profoundly impact Hippo signaling, CIP and tumor suppressor capacity." (PMID 32641858, 2020). "With the exception of ARHGAP35, all genes in this group were already strongly linked to cancer." (PMID 32641858, 2020). "The spectrum of ARHGAP35 mutations in cancer is strongly suggestive of a role as tumor suppressor." (PMID 32641858, 2020). "To test the significance of individual ARHGAP35 alterations in cancer, we selected three recurrent mutations: S229L in the Ras-like domain; E400K in the second FF motif; S866Y in the second pseudoGAP domain; as well as R1284W, which targets the arginine-finger of the catalytically active GAP domain." (PMID 32641858, 2020). "However, investigations should now be performed to correlate ARHGAP35 mutations with clinicopathological features and prognosis of cancer patients." (PMID 31013840, 2019). "ARHGAP35 has known roles in cell migration, invasion and division, neuronal morphogenesis, and gene/mRNA regulation; prior studies indicate a role in cancer in humans and in the developing eyes, neural tissue, and renal structures in mice." (PMID 36450800, 2023). "Overall, this was the first study systematically exploring the effects of ARHGAP35 in GC, thus supporting its universal role in cancer metastasis." (PMID 35758029, 2022). "Most recently, HNRNPL was reported to facilitate the formation of circular Rho GTPase activating protein 35 (ARHGAP35) to promote cancer progression by interacting with the transcription factor TFII-I." (PMID 36012592, 2022). "To explore the potential clinical implications of circARHGAP35 in cancer, we detected the expression of circARHGAP35 and linear ARHGAP35 in a cohort of 110 paired HCC and adjacent non‐tumor tissues." (PMID 34258149, 2021). "To differentiate the roles of circARHGAP35 and linear ARHGAP35 in cancer, we designed three siRNAs specifically targeting the backsplice junction of circARHGAP35, its linear transcript, and both these transcripts, respectively." (PMID 34258149, 2021). "We also found that the circARHGAP35 protein promoted tumor progression by interacting with TFII‐I, while ARHGAP35 inhibited cancer cell migration and invasion by limiting RhoA activity." (PMID 34258149, 2021). "circARHGAP35 and linear ARHGAP35 are observed to have antithetical expression and functions in cancer." (PMID 34258149, 2021). "In this study, we identified a novel circRNA termed as circARHGAP35, originating from the locus of the tumor suppressor gene ARHGAP35, and often upregulated in cancer tissues." (PMID 34258149, 2021).
cancer (continued). "Among highly significantly mutated genes in human cancer, ARHGAP35 encoding p190A is unusual in that its role in cancer is poorly understood." (PMID 32641858, 2020). "In the present work, we have directly tested the significance of ARHGAP35 alteration in human cancer cells." (PMID 32641858, 2020). "Here, we demonstrate for the first time that p190A is a tumor suppressor using a xenograft mouse model with carcinoma cells harboring defined ARHGAP35 alterations." (PMID 32641858, 2020). "Exome sequencing analysis of almost 5000 samples from 21 tumor types identifies ARHGAP35 as a candidate gene in cancer among 33 new genes." (PMID 31013840, 2019). "Three genes with mutations were known cancer associated genes (BAP1, ARHGAP35 and SPEN), but they were mutated in a single sample each, and were missense variants with uncertain functional effects." (PMID 27494029, 2016). "Recently, several reports have shown that ARHGAP35 plays an important role in cancer formation and metastasis." (PMID 25136583, 2014). "ARHGAP35 has also been proposed as an important new cancer gene." (PMID 36672927, 2023). "Furthermore, circARHGAP35 protein increased the migratory and invasive abilities of cancer cell lines, while ARHGAP35 protein played the opposite role." (PMID 34258149, 2021). "Notably, our results showed that circARHGAP35 was upregulated in cancer, while its cognate ARHGAP35 mRNA was downregulated." (PMID 34258149, 2021). "In concordance with the RhoA activity results, we found that the overexpression of ARHGAP35 protein significantly reduced actin‐based stress fiber formation and RhoA function in cancer cell lines, while overexpression of circARHGAP35 protein slightly increased stress fiber formation." (PMID 34258149, 2021). "However, the significance of such findings is difficult to assess, because the role of ARHGAP35 in cancer is poorly defined." (PMID 32641858, 2020). "The ARHGAP35 gene encoding p190A RhoGAP (p190A) is significantly altered by both mutation and allelic deletion in human cancer, but the functional implications of such alterations are not known." (PMID 32641858, 2020). "Altogether, these data demonstrated that ARHGAP35 is a new identified cancer gene." (PMID 31013840, 2019). "Moreover, we identified four novel candidate cancer-associated genes (CTCF, ARHGAP35, NF1, and KDR) which may be crucial in the carcinogenesis of EEC." (PMID 30886832, 2019). "Studies found that CircARHGAP35 has a cancer-promoting effect in HCC, whereas the parent gene ARHGAP35 of CircARHGAP35 has a cancer-suppressing effect." (PMID 34526007, 2021). "Since EMT is considered to be a significant factor during the initiation of cancer metastasis, reversing EMT could be another mechanism of ARHGAP35 to suppress GC metastasis." (PMID 35758029, 2022).
tumor (28 papers, 2010 to 2025). "Actually, a previous study also highlighted the intrinsic association of ARHGAP35 and E-cadherin expression in the regulation of tumor growth." (PMID 35758029, 2022). "Most ARHGAP35 mutations are nonsense mutations and frameshift deletions/insertions supporting a tumor-suppressor role for p190A." (PMID 36516886, 2022). "Such efforts will also aid in interpreting the significance of individual ARHGAP35 mutations in tumor samples." (PMID 32641858, 2020). "To explore the role of recurrent ARHGAP35 mutations in tumor suppression, we injected groups of 10–12 athymic mice with 5 × 106 H661 cells expressing either p190A(E400K), p190(R1284W), p190A(wt), or empty vector control." (PMID 32641858, 2020). "Therefore, the decreased expression levels of ARHGAP35 were associated with advanced tumor-nodule-metastasis (TNM) staging." (PMID 35758029, 2022). "Out of 10,953 patients presently in the TCGA database, 422 patients have 458 ARHGAP35 mutations in tumor samples of which 103 mutations are recurrent; defined as three or more tumors with mutation of a given residue, excluding multiple samples from the same individual (cbioportal.org)." (PMID 32641858, 2020). "The mutational spectrum for ARHGAP35 is suggestive of a tumor suppressor function." (PMID 32641858, 2020). "Activation of ARHGAP35 causes RhoA inactivation and inhibits cell invasion, while its inactivation could play a role in tumor development." (PMID 30886832, 2019). "Another study reported that TRIM65 promotes tumor proliferation and invasion via the ubiquitin-mediated degradation of Rho GTPase-activating protein 35 (ARHGAP35)." (PMID 41385185, 2025). "ARHGAP35, as a tumor suppressor, induces CDH1 expression and cooperates with E-cadherin to activate LATS kinase and inhibit tumor cell growth." (PMID 38263362, 2024). "Knockout of ARHGAP35 in transwell and wound healing experiments also reversed the ability of shFTO+shALKBH5 to inhibit tumor cell migration." (PMID 38263362, 2024). "ARHGAP35 is the downstream target of the synergistic regulation of shFTO and shALKBH5 and acts as a tumor suppressive factor to inhibit the malignant biological behavior of NPC." (PMID 38263362, 2024). "In conclusion, these experiments confirmed that ARHGAP35 is a tumor suppressor and inhibits malignant progression in NPC." (PMID 38263362, 2024). "The results showed that ARHGAP35, a tumor suppressor, was downregulated in GC tissues and its decreased expression was associated with the metastatic status of GC." (PMID 35758029, 2022). "The low expression of ARHGAP35 is also related to a poor prognosis in tumor patients." (PMID 38263362, 2024). "Among them, after DG exposure, standouts include the strong downregulation (logFC = −4) of GTPase activating protein 1 (RACGAP1) and Rho GTPase activating protein 35 (ARHGAP35), which are putative oncoproteins whose overexpression is linked with different tumor types." (PMID 37755964, 2023). "Furthermore, ARHGAP35 was downregulated in patients with GC and its expression was further decreased in metastatic GC, thus supporting the tumor suppressor nature of ARHGAP35." (PMID 35758029, 2022). "Collectively, these findings suggest that circARHGAP35 and linear ARHGAP35 exert antithetical roles in tumors: circARHGAP35 promotes tumor cell growth, migration, invasion, and metastasis, while linear ARHGAP35 acts as a tumor suppressor and inhibits cell migration and invasion." (PMID 34258149, 2021). "Respectively 3/20 G3 HRO tumours were specified by ARHGAP35 at 19q13.32 and by FOXA2 at 20p11.21." (PMID 28486536, 2017). "Supporting our results, recent studies have exhibited that the dysregulation of ARHGAP35 promotes tumor growth, infiltration, and metastases and subsequently might result in poor prognosis of tumors." (PMID 25136583, 2014).
tumor (continued). "In addition, through subcutaneous tumorigenesis and IHC staining assays in nude mice, we found that downregulation of ARHGAP35 could reverse the inhibition of NPC tumor growth by promoting apoptosis in nude mice after combined knockout of FTO and ALKBH5." (PMID 38263362, 2024). "Similarly, in vivo imaging experiments and HE lung tissue staining experiments revealed that shFTO+shALKBH5 tumor metastasis of NPC in nude mice could be reversed by downregulation of ARHGAP35." (PMID 38263362, 2024). "Thus, present and future investigations into the tumor suppressor function of p190A may directly impact future personalized targeted therapy for malignancies with ARHGAP35 alteration." (PMID 32641858, 2020). "Among these cases receiving the radical treatment, shorter median overall survival time (MST) and shorter median tumor recurrence-free survival time (MRT) were found in cases having risk genotypes (including ARHGAP35 rs1052667-CT and -TT) than in those without risk genotypes." (PMID 25136583, 2014). "Moreover, we observed HNRNPL was significantly upregulated in HCC compared to matched non‐tumor (NT) liver tissues, and is positively correlated with circARHGAP35 but not linear ARHGAP35 in HCC tissues and cells." (PMID 34258149, 2021).
ARHGAP35 also shares sentences with these, for which no sentence is quoted: melanoma (5 papers); bladder cancer (2); hepatocellular carcinoma (2); prion disease (2); scrapie (2); anaplastic thyroid carcinoma (1); Anophthalmia (1); Anorexia (1); Ataxia (1); autism (1); Cognitive impairment (1); coloboma (1); demyelinating CNS diseases (1); demyelinating disease (1); Endometrial tumors (1); esophageal cancer (1); glioblastoma (1); hepatoblastoma (1); hereditary cancer (1); Hydroureter (1); idiopathic pulmonary fibrosis (1); insulinomas (1); Intellectual disability (1); kidney (1); Kidney Cyst (1); lymph node metastases (1); metastatic colorectal cancer (1); metastatic melanoma (1); nasopharyngeal carcinoma (1); neurodegenerative disease (1).
A further 9 diseases each share a sentence with ARHGAP35 in 1 paper.